ACTN1 (actinin alpha 1)
Description:
F-actin cross-linking protein which is thought to anchor actin to a variety of intracellular structures. Association with IGSF8 regulates the immune synapse formation and is required for efficient T-cell activation.
Synonyms: BDPLT15
Tractability: Antibody: UniProt places it where antibodies can reach, with high confidence; its Gene Ontology location is reachable by antibodies, with high confidence; the Human Protein Atlas places it where antibodies can reach. PROTAC: ubiquitination databases record sites on it; its protein half-life has been measured.
Gene: Protein-coding gene on chromosome 14 (68,874,121 to 68,980,277, reverse strand). Ensembl gene ENSG00000072110.
Subcellular location: Cytoplasm, cytoskeleton; Cytoplasm, myofibril, sarcomere, Z line; Cell membrane; Cell junction; Cell projection, ruffle
Subcellular location (Human Protein Atlas): Actin filaments; Focal adhesion sites; Plasma membrane; Cytosol; Primary cilium; Primary cilium transition zone
Pathways (Reactome):
Signal Transduction: RHOBTB2 GTPase cycle; RHOD GTPase cycle; RHOF GTPase cycle
Cell-Cell communication: Nephrin family interactions; Regulation of cytoskeletal remodeling and cell spreading by IPP complex components
Extracellular matrix organization: Syndecan interactions
Hemostasis: Platelet degranulation
Gene Ontology:
Molecular function: actin filament binding; double-stranded RNA binding; integrin binding; protein binding; protein homodimerization activity; structural constituent of postsynapse; transcription coactivator activity; transmembrane transporter binding; vinculin binding; calcium ion binding; cytoskeletal protein binding; identical protein binding; structural molecule activity
Biological process: actin filament network formation; actin filament organization; focal adhesion assembly; platelet activation; platelet aggregation; platelet formation; platelet morphogenesis; actin cytoskeleton organization; muscle cell development; regulation of apoptotic process; actin filament bundle assembly; anatomical structure formation involved in morphogenesis; positive regulation of DNA-templated transcription; postsynapse organization; supramolecular fiber organization
Cellular component: actin filament; cell projection; cell-cell junction; cytoplasm; extracellular exosome; extracellular region; focal adhesion; glutamatergic synapse; plasma membrane; ruffle; stress fiber; Z disc; cell junction; cortical actin cytoskeleton; cytosol; platelet alpha granule lumen; pseudopodium; actin cytoskeleton; anchoring junction; brush border; cytoskeleton; fascia adherens; sarcomere; synapse
Genetic constraint (gnomAD): Loss-of-function variants: 30 observed, 122.95 expected, observed/expected ratio (o/e) 0.24, 90% interval 0.18 to 0.33. The upper end of that interval is the gene's LOEUF score, 0.33, which puts it in group 1 of 6, group 1 being the genes least tolerant of losing a copy. Missense variants: 764 observed, 1,272.4 expected, observed/expected ratio (o/e) 0.6, 90% interval 0.56 to 0.64. Synonymous variants: 429 observed, 493.65 expected, observed/expected ratio (o/e) 0.87, 90% interval 0.8 to 0.94.
Gene-disease validity (ClinGen):
ClinGen rates the evidence that ACTN1 causes each of these diseases.
platelet-type bleeding disorder 15 (autosomal dominant): Definitive. Any inherited bleeding disorder, platelet-type in which the cause of the disease is a mutation in the ACTN1 gene.
Homologues: Orthologues: macaque ACTN1 (99% identical), guinea pig ACTN1 (99% identical), rat Actn1 (99% identical), dog ACTN1 (97% identical), mouse Actn1 (97% identical), tropical clawed frog actn1 (94% identical), zebrafish actn1 (91% identical), chimpanzee ACTN1 (88% identical), pig ACTN1 (86% identical), rabbit ACTN1 (84% identical), Drosophila melanogaster Actn (68% identical). Paralogues in human: ACTN4 (84% identical), ACTN2 (78% identical), ACTN3 (76% identical), SPTBN1 (31% identical), SPTBN4 (31% identical), SPTBN2 (30% identical), SPTB (30% identical), PLEC (27% identical), SPTBN5 (27% identical), DST (25% identical), MACF1 (25% identical), SYNE1 (25% identical), and 24 more.
Diseases named in the same sentence as ACTN1 in open-access papers:
ACTN1 is named in the same sentence as 93 diseases in open-access papers, as found by Europe PMC text mining. Sharing a sentence is not in itself a finding about the gene and the disease. The quoted sentences say what the papers report.
breast carcinoma (13 papers, 2019 to 2025). "ACTN1 is an actin-binding cytoskeletal protein that is frequently overexpressed in human breast cancers and linked with the poor prognosis in basal-like breast cancer." (PMID 38480932, 2024). "ACTN1 has been proved to be associated with the poor prognosis in breast cancer, oral squamous cell carcinoma, and acute lymphoblastic leukemia." (PMID 33413564, 2021). "In breast cancer cells, increased levels of ACTN1 cause unstable adhesion, thus promoting the collective migration of cancer cells." (PMID 32670437, 2020). "Studies have shown that ACTN1 is highly expressed in breast cancer and is associated with its prognosis." (PMID 30879239, 2020). "Studies suggest that elevated ACTN1 expression destabilizes E-cadherin-based adhesions, potentially enhancing the migratory capacity of breast cancer cells." (PMID 40818124, 2025). "Oroxylin A, designed for targeting ACTN1, can remodel the interstitial microenvironment of breast cancer and inhibit tumor metastasis." (PMID 38307919, 2024). "Oroxylin A inhibits ACTN1 expression, inactivates cancer-related fibroblasts, and represses breast cancer metastasis." (PMID 36742137, 2023). "Oroxylin A was shown to have a beneficial therapeutic effect on breast cancer by specifically binding to α-actinins 1 (ACTN1), thereby inhibiting ACTN1 expression to prevent cancer cell metastasis." (PMID 36985705, 2023). "The possible reason for this is the increased ACTN1 expression leads to destabilization of E-cadherin-based adhesions and thus promotes the migratory potential of breast cancer cells." (PMID 36278174, 2022). "In case of basal-like breast cancer the increased expression of ACTN1 contributes to the transition to amoeboid movement." (PMID 36278174, 2022). "Intracellular delivery of the actinin-1 (ACTN1) complexed with CA in breast cancer cells showed a significant reduction of viability in MCF-7 and 4T1 cell lines, while, in MDA-MB-231, no such effect was observed." (PMID 31269666, 2019). "In the current study, we successfully targeted dysregulated CTNNA1, CTNNB1, TLN1, VCL, PXN, and ACTN1 genes by delivering respective siRNAs with the help of nano-sized CA particles in breast cancer cells as well as in a murine breast cancer model." (PMID 31269666, 2019). "To do this, we examined existing datasets from genome-wide CRISPR-Cas9 and RNAi screens of several breast cancer cell lines, and found that the candidate gene ACTN1 was essential in 12 out of 18 TNBC cell lines, suggesting its importance for the viability of TNBC cells." (PMID 38480932, 2024). "Previous studies also indicated that ACTN1 knockdown could inhibit the metastasis of breast cancer and oral squamous cell carcinoma." (PMID 36742137, 2023). "Targeting ACTN1 by Oroxylin A could remodel stromal microenvironment and restrain breast cancer metastasis." (PMID 33413564, 2021). "Simultaneously, the malicious roles of ACTN1 in breast cancer have also been proved." (PMID 34546849, 2021). "Similarly, study showed targeting ACTN1 by Oroxylin A could remodel stromal microenvironment and restrain breast cancer metastasis." (PMID 38480932, 2024).
Thrombocytopenia (13 papers, 2013 to 2025). A reduction in the number of circulating thrombocytes. "Recent studies have revealed that mutations in the ACTN1 gene are associated with inherited thrombocytopenia, but little is known about the exact role of α-actinin-1 in thrombocytopoiesis and its underlying mechanism." (PMID 41153762, 2025). "ACTN1 involves platelet functions, with mutations potentially causing mild thrombocytopenia with minimal clinical impact." (PMID 39757988, 2025). "As a matter of fact, our survey of the other five thrombocytopenia-causing ACTN1 missense mutations revealed that, apart from p.Gln32Lys, all the other mutations are also CpG mutations, too." (PMID 24069336, 2013). "ACTN1 is mainly expressed in platelets, and its variants are associated with thrombocytopenia." (PMID 38575196, 2024). "Finally, the discovery of causative ACTN1 mutations in subjects with isolated thrombocytopenia shows again the pivotal importance of genetic findings in disease diagnosis and treatment." (PMID 24069336, 2013). "RUNX1, ANKRD26, MYH9, ACTN1, and GP1BB had ranks of 1, 3, 8, 16, and 74, respectively, with none of the other loci in the top 20 ranks being known to be implicated in thrombocytopenia." (PMID 28669401, 2017). "Consistent with these previous descriptions, amongst the 21 index cases and three pedigree members with ACTN1 variants in the BRIDGE-BPD analysis, 23/24 (96%) displayed thrombocytopenia and 22/24 (92%) large platelets." (PMID 25949529, 2015). "Our study concurred with the recently published Japanese study, adding ACTN1 to the growing list of thrombocytopenia genes." (PMID 24069336, 2013). "Our study concurred with a recently published whole-exome sequence analysis of six small Japanese families with congenital macrothrombocytopenia, adding ACTN1 to the growing list of thrombocytopenia genes." (PMID 24069336, 2013). "ACTN1-related thrombocytopenia was diagnosed in three male patients (2%)." (PMID 36507135, 2022). "In addition, congenital abnormality of the urinary tract, cardiac valve diseases, splenomegaly, and gallbladder anomalies were reported in two patients affected by ACTN1-related thrombocytopenia." (PMID 36507135, 2022). "Among three patients with ACTN1-related thrombocytopenia, one patient (33%) was asymptomatic." (PMID 36507135, 2022). "Moreover, mutations in cytoskeleton-associated proteins, such as FLNA, ACTN1, MYH9, or TUBB1, were identified in patients affected by proplatelet defects and thrombocytopenia." (PMID 30336771, 2018). "Interestingly, two family members without thrombocytopenia in our pedigree carried the ACTN1 p.Arg46Gln missense mutation." (PMID 24069336, 2013). "We found that GP1BA-, MYH9-, ACTN1-, and ANKRD26-related thrombocytopenias are the most frequent diseases diagnosed with a highly variable clinical course and long-term prognosis." (PMID 36507135, 2022). "It has been reported that bleeding in ACTN1-related thrombocytopenia was absent or mild." (PMID 39757988, 2025).
hepatocellular carcinoma (7 papers, 2021 to 2024). A malignant tumor that arises from hepatocytes. "Emerging evidence have uncovered the regulatory role of ACTNs in tumorigenesis, however, the expression pattern, biological functions, and underlying mechanism of ACTN1 in hepatocellular carcinoma (HCC) remain largely unexplored." (PMID 33413564, 2021). "Silencing ACTN1 expression has been demonstrated to impede the proliferation of hepatocellular carcinoma (HCC)." (PMID 38836761, 2024). "Similarly, the aberrant expression of ACTN1 has been observed in oral, colon, hepatocellular carcinoma, acute myeloid leukemia, and lung adenocarcinoma, contributing to tumor oncogenesis and metastasis by diverse signaling pathways such as Hippo signaling and FAK/Src/JAK2/STAT3 signaling." (PMID 34546849, 2021). "In hepatocellular carcinoma (HCC), ACTN1 has been demonstrated to promote tumorigenesis of HCC by inhibiting Hippo signaling." (PMID 34546849, 2021).
oral squamous cell carcinoma (7 papers, 2021 to 2024). "The Catulin-GFP plus population also showed a upregulation of ACTN1 gene, of which the high expression level was recently associated with the clinical stage, node metastasis, and poor prognosis for oral squamous cell carcinoma (OSCC) patients." (PMID 35008571, 2021). "ACTN1 has been reported to predict poor prognosis of acute lymphoblastic leukemia, oral squamous cell carcinoma, and breast cancer." (PMID 38307919, 2024). "ACTN1 upregulation is related to poor prognosis, and ACTN1 knockdown inhibits cell proliferative ability and metastasis of oral squamous cell carcinoma (OSCC)." (PMID 36742137, 2023). "Reports have indicated that aberrant ACTN1 expression was responsible for the EMT in several cancers, such as the oral squamous cell carcinoma." (PMID 34546849, 2021).
Macrothrombocytopenia (6 papers, 2013 to 2017). "ACTN1 mutations cause macrothrombocytopenia, a platelet disorder characterized by excessive bleeding." (PMID 26312134, 2015). "Candidate gene analysis complemented by targeted next-generation sequencing identified a missense mutation (c.137GA; p.Arg46Gln) in the alpha-actinin 1 gene (ACTN1) that segregated with macrothrombocytopenia in this large pedigree." (PMID 24069336, 2013). "Six missense mutations in the ACTN1 gene, including p.Arg46Gln, have been recently described in six small Japanese families with macrothrombocytopenia using whole-exome sequencing combined with Sanger sequencing." (PMID 24069336, 2013). "In this study, we successfully identified a missense mutation in the ACTN1 gene (p.Arg46Gln) as the cause of an autosomal dominant form of isolated macrothrombocytopenia in a large, six-generation Caucasian pedigree." (PMID 24069336, 2013). "Due to the large number of the subjects studied in our pedigree, we were able to establish a clear model of autosomal dominant inheritance of the ACTN1-associated macrothrombocytopenia and demonstrated a high penetrance of the ACTN1 p.Arg46Gln mutation." (PMID 24069336, 2013). "Of these, ACTN1, which encodes alpha-actinin 1, was regarded as the most likely candidate by virtue of its functional role in the cytoskeleton and by analogy to some of the known macrothrombocytopenia genes, such as MYH9, FLNA and TUBB1." (PMID 24069336, 2013). "We now describe the properties of SimReg’s output by focusing on a gene, ACTN1 (MIM: 102575), that has recently been reported to harbor rare variants responsible for reduced platelet number and increased platelet size (macrothrombocytopenia)." (PMID 26924528, 2016). "These independent findings from two distinct populations (Caucasian and Asian) strongly support the involvement of the ACTN1 gene in macrothrombocytopenia." (PMID 24069336, 2013). "Causal variants in ACTN1 have been identified in 18 recently reported pedigrees with a phenotype that comprises mild bleeding and macrothrombocytopenia with no other syndromic features." (PMID 25949529, 2015).
colon cancer (5 papers, 2015 to 2024). "Our finding that ACTN1 and ACTN4 show differential affinities for ZYX may provide the molecular mechanism underlying the phenotypic outcome of ACTN overexpression in colon cancer cells." (PMID 25860875, 2015). "In addition, alpha-actinin 1 (ACTN1), one of the genes identified in the network, is associated with focal adhesion formation, and its phosphorylation modulates pressure-induced adhesion in colon cancer cells." (PMID 26543234, 2015). "We first quantified the relative expression levels of endogenous ACTN1 and ACTN4 proteins in several colon cancer cell lines using purified recombinant proteins as external controls." (PMID 25860875, 2015). "The results from both DLD-1 cells and SW480 cells indicate that the biased expression of ACTN isoforms dictates the invasive property of colon cancer cells; higher relative expression of ACTN4 over ACTN1 tends to favor invasive phenotypes." (PMID 25860875, 2015). "ACTN1 may positively interact with ITGA9 to promote proliferation, invasion, and EMT in colon cancer." (PMID 39228892, 2024).
astrocytoma (4 papers, 2015 to 2021). "Previously, ACTN1 has been reported to play contrasting roles in RhoA signaling of astrocytoma cells." (PMID 33413564, 2021). "Actn1 (α-Actinin 1) was found to play roles in the survival, motility, and RhoA signaling of astrocytoma cells." (PMID 29785346, 2018). "During the occurrence and development of astrocytoma, ACTN1 and ACTN4 are regulated differently, and their effects on the malignant development of astrocytoma cells are opposite." (PMID 32670437, 2020). "However, it also has been shown that ACTN1 and ACTN4 contribute to distinct malignant properties of astrocytoma cells and that ACTN4 may be more important for cell motility and cell adhesion in some cell lines." (PMID 25885339, 2015).
dilated cardiomyopathy (4 papers, 2019 to 2023). Cardiomyopathy which is characterized by dilation and contractile dysfunction of the left and right ventricles. "Actn1 is reexpressed in cardiomyocytes of patients with myocardial infarction, aortic stenosis, and dilated cardiomyopathy." (PMID 32774516, 2020). "Notably, among these proteins, MYL2, ACTN1, MYLK, COL1A2, COL6A2, and COL6A3 have been associated with dilated cardiomyopathy and hypertrophic cardiomyopathy pathogenic processes in previous studies." (PMID 37649075, 2023). "In addition to Actn1, we observed also a strong expression of Actn4 in cardiomyocytes of patients with dilated cardiomyopathy suggesting similar functions." (PMID 32774516, 2020).